INS (insulin)
Diseases named in the same sentence as INS in open-access papers (continued):
Sharing a sentence is not in itself a finding about the gene and the disease.
sarcopenia (continued). "The identification of insulin signaling, growth hormone pathways, and longevity regulation links miR‐22 to systemic endocrine and metabolic control relevant to both primary and secondary sarcopenia." (PMID 41239553, 2025). "Importantly, sarcopenia is considered detrimental to glucose uptake as it reduces the muscle mass available for insulin-stimulated glucose processing." (PMID 41357171, 2025). "Although the mechanism of sarcopenia in T2DM remains unclear, decreased endogenous insulin secretion has been implicated in reducing muscle mass in diabetic patients." (PMID 39058051, 2024). "Sarcopenia may lead to altered systemic inflammatory response and endocrine function and can reflect poor nutritional status and insulin resistance." (PMID 39604574, 2024). "In order to further evaluate the effect of CMP on the protein expression of H2O2-induced muscular atrophy in the insulin resistance pathway and the protein synthesis signaling pathway, sarcopenia-related proteins after treatment with CMP were detected by Western blots." (PMID 38397848, 2024). "As mitochondria work as energy factories in cells, decreased mitochondrial content and impaired mitochondrial function can lead to insulin insensitivity via lipid deposition and reactive oxygen species accumulation, inhibiting muscle renewal and increasing the chances of sarcopenia." (PMID 39043630, 2024). "The link between sarcopenia and renal hyperfiltration may be based on the interplay of various factors, including oxidative stress, insulin resistance and overactivation of the renin–angiotensin–aldosterone system." (PMID 38594601, 2024). "The link between MASLD severity and sarcopenia may be due to the role of skeletal muscle in insulin-mediated glucose absorption." (PMID 38919220, 2024). "Furthermore, two polymorphisms within the FNDC5 promoter (rs16835198 and rs726344) are both known to impact insulin sensitivity, and insulin sensitivity is a contributing factor for developing sarcopenia." (PMID 38790190, 2024). "In previous studies, patients with sarcopenia exhibited lower insulin levels." (PMID 38594634, 2024). "In addition, the review provides insights regarding lipid metabolism on sarcopenia, with an emphasis on the effects of inflammation and insulin resistance." (PMID 39186818, 2024). "Along with its importance as a biomarkers, the knowledge of these connections between bone and other tissues raises therapeutic hypothesis, such as possible beneficial effects with the exogenous administration of osteocalcin on insulin secretion in sarcopenia." (PMID 38634076, 2024). "However, individuals with sarcopenia, particularly women, frequently exhibit a notable reduction in insulin sensitivity." (PMID 38338247, 2024). "Since the insulin sensitivity related to sarcopenia is impaired, the anabolism of insulin in skeletal muscle may be gradually lost in T2DM patients." (PMID 38509497, 2024). "The potential mechanistic underpinnings delineating the nexus between sarcopenia and abnormal liver function encompass a spectrum of contributory facets, as follows: Firstly, sarcopenia may adversely affect liver function through insulin resistance." (PMID 38076231, 2023). "Glucose-lowering drugs, such as insulin, metformin, and thiazolidinediones, improve insulin sensitivity and might have a beneficial effect on parameters of sarcopenia." (PMID 38004100, 2023). "This supports previous studies suggesting that improving insulin sensitivity could be beneficial in sarcopenia and the progression of CKD." (PMID 36994079, 2023). "Additionally, aerobic-based exercise training (AT) has been proposed as a beneficial intervention for sarcopenia due to its capacity to promote mitochondrial biogenesis and insulin sensitivity while reducing oxidative stress." (PMID 37508325, 2023).
sarcopenia (continued). "This hypothesis is also supported by our results, indicating that patients with NAFLD and sarcopenia experience a worse metabolic condition, implied by the higher values of waist and hip circumferences, insulin levels, as well as HOMA-IR scores." (PMID 37373921, 2023). "Myokines regulate energy expenditure, insulin sensitivity, lipolysis, free fatty acid oxidation, adipocyte browning, and glycogen synthesis and catabolism, and sarcopenia may play a role in the progression of cardiovascular disease via these mechanisms." (PMID 37370012, 2023). "Regarding sarcopenia, since skeletal muscle is the primary tissue responsible for insulin-mediated glucose disposal, insulin resistance, which is the main pathology of NAFLD, might have a common role in skeletal muscle and liver." (PMID 36869158, 2023). "Furthermore, some related studies have suggested that insulin, estrogen, androgen, growth hormone and glucocorticoid changes were also involved in the pathogenesis of sarcopenia." (PMID 37274285, 2023). "Insulin sensitivity as a predictor of sarcopenia is a less well-studied entity." (PMID 37685565, 2023). "Furthermore, sarcopenia is recognized as a separate mechanistic driver of disease via reduced skeletal muscle mass and reduced insulin-sensitized glucose disposition." (PMID 36937977, 2023). "Among the various antidiabetic agents, we found a positive association between insulin use and sarcopenia and a negative association between sulphonylurea use and sarcopenia." (PMID 37685565, 2023). "However, a Japanese study reported that individuals with T2DM taking insulin showed an attenuation in the progression of sarcopenia." (PMID 37685565, 2023). "Finally, coffee has been shown to induce autophagy, improve insulin sensitivity, increase glucose uptake, slow the progression of sarcopenia, and maintain muscle mass, which are closely related to physical function and frailty." (PMID 36819700, 2023). "Even though poor glycemic control and insulin therapy are reported to be associated with sarcopenia in T2DM, T1DM may be a stronger risk factor for sarcopenia." (PMID 38068772, 2023). "Measures that increase intracellular phosphate and improve insulin sensitivity and restore energy pools may represent a new approach for preventing and reversing sarcopenia." (PMID 36994079, 2023). "Furthermore, anti-diabetic agents such as metformin play a protective role against sarcopenia through increased insulin sensitivity and glucose hemostasis." (PMID 35395731, 2022). "Sarcopenia is characterized as an age-related loss of muscle mass that results in negative health consequences such as decreased strength, insulin resistance, slowed metabolism, increased body fat mass, and a substantially diminished quality of life." (PMID 35454154, 2022). "In addition, we calculate the usefulness of AST/ALT and INS*PA in predicting sarcopenia among all participants, male participants, and female participants, respectively." (PMID 35370985, 2022). "Importantly, since muscle tissue is key in glucose disposal, sarcopenia itself diminishes insulin-mediated glucose disposal, which is conducive to insulin resistance." (PMID 36686421, 2022). "In our study, patients with sarcopenia had higher insulin levels." (PMID 36419004, 2022). "The mechanisms underlying low insulin in sarcopenia in diabetic and non-diabetic older individuals is not completely understood." (PMID 36482911, 2022). "AST/ALT and INS*PA were not affected by metabolic factors and had better diagnostic efficacy for sarcopenia." (PMID 35370985, 2022). "Other factors related to sarcopenia include motor neuron degeneration, genetic factors, inflammatory factor and insulin resistance." (PMID 35935249, 2022).
sarcopenia (continued). "Sarcopenic skeletal muscles are known to be insulin resistant even in the setting of low whole-body fat stores, and considering that skeletal muscle is a primary site of both insulin action and glucose uptake/storage, sarcopenia contributes significantly to systemic metabolic syndrome." (PMID 35244142, 2022). "The AUC of the AST/ALT/(INS*PA)*10,000 used to diagnose sarcopenia was 0.727." (PMID 35370985, 2022). "Meanwhile, insulin levels were associated with muscle mass among sarcopenia and nonsarcopenia group." (PMID 36419004, 2022). "We used fasting insulin*prealbumin (INS*PA) to amplify the difference between sarcopenia and non-sarcopenia groups and to evaluate its potential as a diagnostic biomarker for sarcopenia." (PMID 35370985, 2022). "Suppression of insulin signaling can disrupt the phosphatidylinositol-3-kinase pathway, which promotes the reduced synthesis of proteins, impairing muscle function and integrity and contributing to the development of sarcopenia." (PMID 36362238, 2022). "In individuals with sarcopenia, appendicular muscle mass index defined as muscle mass relative to height is mostly found positively associated with insulin resistance, while this correlation is negative in terms of muscle mass relative to body weight." (PMID 36482911, 2022). "After dividing the two calculated values, the AST/ALT/(INS*PA)*10,000 was obtained, and the AUC of the new calculated value used to diagnose sarcopenia was 0.727, with a cutoff value of >7.75, and the sensitivity and specificity were 68.0 and 66.7, respectively." (PMID 35370985, 2022). "Among insulin signaling, the PI3K/Akt pathway is highly associated with the cause of sarcopenia." (PMID 35565712, 2022). "Fat accumulation is associated with pro-inflammatory cytokines, oxidative stress, and insulin resistance, and also contributes to muscle fiber atrophy and mitochondrial dysfunction, potentially contributing to the development and progression of sarcopenia." (PMID 36522628, 2022). "In conclusion, the current study shows that the independent risk factors for sarcopenia in middle-aged and older patients are serum AST/ALT >1.14, INS*PA <1,833 μU/ml*g/L, FT3 <4.48 pmol/L, VitD <18.5 ng/ml (in male participants), PTC >336 nmol/L, and DBP <81 mmHg (in female participants)." (PMID 35370985, 2022). "Since these serum biomarkers are inexpensive and can be obtained easily from biochemical routine, regular follow-up of AST/ALT and INS*PA may be an effective strategy in sarcopenia screening and management." (PMID 35370985, 2022). "Chronic inflammation affects the aging body with multiple impairments, for example hormonal and/or epigenetic alterations, microvascular changes, or insulin dysregulation, which may coalesce promoting sarcopenia." (PMID 33926079, 2021). "Moreover, in the last years multiple pre-clinical studies have reported a large number of myokines involved in onset of sarcopenia, elucidating an increasing complexity in the cross talk between insulin-sensitive tissues." (PMID 34858322, 2021). "Patients with sarcopenia had lower levels of fasting insulin than the healthy." (PMID 34956096, 2021). "Indeed, sarcopenia reduces glucose uptake and increases insulin resistance which in turn accelerates fibrosis progression." (PMID 35111794, 2021). "Moreover, blockade of sarcopenic markers, such as myostatin, not only prevents sarcopenia but also increases insulin sensitivity in old mice." (PMID 34067004, 2021). "Since insulin deficiency is an independent risk factor for sarcopenia, the next question may be whether insulin treatment can protect against sarcopenia." (PMID 34063269, 2021). "All glucose-lowering drugs for T2DM can beneficially impact on some of the mechanisms possibly involved in sarcopenia; in fact, they improve blood glucose control and insulin sensitivity, inhibit AGEs formation, and improve inflammation and the oxidative stress." (PMID 34440727, 2021).
sarcopenia (continued). "High IRS2 mRNA levels in the older age group of these healthy and highly functional individuals is also consistent with the hypothesis that compromised insulin signaling plays a role in the development of sarcopenia and frailty." (PMID 33795677, 2021). "Considering that skeletal muscle protein synthesis in the elderly is resistant to the anabolic effects of insulin and that this is an important factor in the development of sarcopenia, it is necessary to examine the changes in blood indices after protein intake in more detail." (PMID 34993224, 2021). "In this paper, we report for the first time the beneficial effects of an olive leaf extract rich in flavonoids and secoiridoids, administered at a dose of 100 mg/kg/day for three weeks, on sarcopenia and insulin sensitivity in skeletal muscle and adipose tissue of aged rats." (PMID 34067004, 2021). "Furthermore, elderly individuals with the INS/INS genotype had increased chances (p = 0.010; OR:2.943; 95%CI:1.301–6.654) for the development of sarcopenia." (PMID 34683186, 2021). "AWGS1 significantly associated age, depressive status, body mass index (BMI), hemoglobin, vitamin D, and insulin level with sarcopenia, but AWGS2 did not associate any of these factors with sarcopenia." (PMID 34943268, 2021). "The effect of OLE increasing insulin sensitivity in skeletal muscle may be related, at least in part, to its positive effect on sarcopenia since both phenomena are intimately related." (PMID 34067004, 2021). "Insulin might promote myoblast activation and division, which would constitute the sarcopenia preventive effect of DPP4 inhibitors." (PMID 32868771, 2020). "Sarcopenia and systemic weakness among the elderly have been correlated with intestinal dysbiosis, contributing to increased intestinal barrier permeability, elevated blood LPS levels, activation of the immune system, and areduction of insulin sensitivity." (PMID 32443396, 2020). "Such a feeding regimen could also improve protein synthesis, by increasing plasma AA and insulin and may be useful to combat sarcopenia in aging cats by increasing LBM." (PMID 32946478, 2020). "Our study also showed that other hypoglycemic drugs (sulfonylureas/glinides, alpha-glucosidase inhibitors, and insulin) might exert a protective effect on sarcopenia." (PMID 33083494, 2020). "Alterations in inflammatory status, insulin resistance, lipid homeostasis and mitochondrial activity appear as a key factors that could be involved in sarcopenia during RA." (PMID 31952247, 2020). "The pathogenesis of sarcopenia involves systemic inflammation, impaired muscle protein synthesis, increased muscle cell apoptosis, mitochondrial dysfunction in skeletal muscle tissue, and insulin resistance." (PMID 32168799, 2020). "Current clinical evidence indicates that insulin treatment could attenuate the deterioration of sarcopenia in T2DM patients." (PMID 32695832, 2020). "Furthermore, GJG has also been reported to suppress sarcopenia via the insulin growth factor-1/insulin pathway, maintains the expression of mitochondrial-related transcription factors, and suppresses the expression of TNF-α." (PMID 32766269, 2020). "Increased whole-body lean mass in elderly subjects with sarcopenia improves insulin sensitivity." (PMID 31814802, 2019). "IL-4 has dual potential to act as an adjuvant therapeutic target for sarcopenia to preserve muscle mass and insulin resistance to improve insulin sensitivity, which implicates the regulation of immune system to the muscle differentiation and exercise performance." (PMID 31814802, 2019). "Reduced insulin sensitivity and sarcopenia, which are common age-related disorders, could contribute to a slowdown in the uptake of circulating LNAA into muscles, which would lead to a lower blood TRP: LNAA ratio and to lower brain levels of TRP." (PMID 31011478, 2019).
sarcopenia (continued). "Although the mechanism by which DM affects sarcopenia remains obscure, one possible explanation might be through the insufficient action of insulin." (PMID 30922266, 2019). "Taken together, dysregulated anabolic and catabolic pathways via insulin signaling and energy metabolism and anabolic sex steroid regulation appear to be primary pathophysiological mechanisms directly related to the development of sarcopenia." (PMID 30302905, 2018). "In addition, goshajinkigan was found to suppress sarcopenia via the insulin/IGF-1 signaling pathway." (PMID 28712265, 2017). "Whether the administration of insulin influences the incident sarcopenia in randomized controlled trials remains to be elucidated." (PMID 28246927, 2017). "Age-related muscle wasting and, subsequently, the development of sarcopenia are influenced by gradually declining physical activity and by several biological processes, such as hypogonadic hormonal changes, fat infiltration, and insulin resistance." (PMID 25040542, 2014). "It has been suggested that muscle metabolism may play a role in the development of sarcopenia, given that impaired insulin sensitivity has been shown to disrupt the anabolic effects on muscle proteins necessary for skeletal muscle conservation." (PMID 22611388, 2012). "Metformin may counter age-related metabolic phenomena, such as sarcopenia, increased body fat and osteopenia, insulin sensitivity and adipokines." (PMID 21241523, 2011). "In the elderly, however, the degree to which sarcopenia is associated with a reduced insulin response and/or the presence of inflammatory factors is not clear." (PMID 20626909, 2010). "We further hypothesize that this association will be stronger in young and middle aged adults than in older adults, in whom sarcopenia may mean a preferential reduction in insulin-resistant fibers." (PMID 22421977, 2010). "Therefore, in the elderly population, early screening for possible sarcopenia and sarcopenic patients, followed by timely interventions such as enhanced physical activity, can not only directly improve insulin sensitivity but also indirectly modulate body composition." (PMID 40504826, 2025). "Additionally, in animal studies, GLP-1RA may have protective effects on skeletal muscle against sarcopenia by increasing insulin sensitivity, inhibiting myostatin expression, and increasing mitochondrial biogenesis." (PMID 40226371, 2025). "Furthermore, sarcopenia reduces tissue responsiveness to insulin, thereby increasing IR." (PMID 39940355, 2025). "Finally, additional work should determine if adding Phyllanthus emblica, Shilajit, and/or chromium to other nutritional approaches to promote muscle accretion, prevent sarcopenia, improve insulin sensitivity, manage blood glucose, and/or promote vascular health would offer additional benefits." (PMID 40573153, 2025). "At the same time, sarcopenia sets in as an inexorable aspect of advancing age, which in turn affects the release of growth-promoting myokines and neurochemicals that could promote the resistance to insulin’s actions." (PMID 39459434, 2024). "Moreover, recent years have seen the emergence of “TNF-α,” “insulin resistance”, “mitochondrial autophagy”, “signal pathways”, and “mechanisms” as focal points in the realm of OS in sarcopenia, encompassing related fundamental research and clinical translation." (PMID 39588187, 2024). "Running, walking, cycling, swimming, or jogging, examples of aerobic exercises, can treat sarcopenia without showing notable changes in body weight, which could be linked to improved insulin action and the regulation of protein synthesis." (PMID 38541736, 2024). "Thus, we hypothesize that L-2-amino-3-oxobutanoic acid may be involved in the pathogenesis of sarcopenia through the modulation of glycine metabolism, potentially affecting insulin sensitivity, antioxidative, and anti-inflammatory capacities." (PMID 38962681, 2024).